RNU6-1313P (RNA, U6 small nuclear 1313, pseudogene)
Gene: Small nuclear RNA gene on chromosome 17 (49,966,075 to 49,966,176, reverse strand). Ensembl gene ENSG00000199492.
Homologues: Orthologues: chimpanzee U6 (99% identical), pig U6 (72% identical), macaque U6 (70% identical), dog U6 (66% identical), guinea pig U6 (62% identical). Paralogues in human: RNU6-38P (80% identical), RNU6-1145P (79% identical), RNU6-812P (79% identical), RNU6-1251P (78% identical), RNU6-477P (78% identical), RNU6-16P (77% identical), RNU6-211P (77% identical), RNU6-39P (77% identical), RNU6-639P (77% identical), RNU6-1089P (76% identical), RNU6-10P (76% identical), RNU6-1214P (76% identical), and 1285 more.